BCL2 (BCL2 apoptosis regulator)
Diseases named in the same sentence as BCL2 in open-access papers (continued):
Sharing a sentence is not in itself a finding about the gene and the disease.
breast carcinoma (continued). "Although ER, Ki-67, and Her2 are routinely analyzed in invasive breast cancer cases, the results also suggest that quantitative image analysis can likely be sequestered to just PR and BCL-2 slides in underprivileged areas for the purpose of predicting breast cancer recurrence." (PMID 30574014, 2018). "Therefore, an increased Bax/Bcl-2 ratio in breast cancer tissues of mice treated with VOE250, supports inhibition of cell survival or induction of apoptotic cascade by VOE." (PMID 29755559, 2018). "In addition, in vivo silencing of Bcl-2 with nanoliposomal Bcl-2 siRNA can inhibit the growth of xenografted ER- and ER+ breast cancers." (PMID 29876007, 2018). "Importantly, the ratio of Bcl-2/Bax was significantly decreased, which suggests that the Bcl-2/Bax plays an important role in breast cancer cell progression regulated by the BEZ235 and TSA combination." (PMID 28060760, 2017). "MiR-34a may participate in the regulation of drug-resistant breast cancer by targeting BCL-2, CCND1, and NOTCH1." (PMID 29290947, 2017). "Similarly, a study has shown a reduction of EGFR activation in EPA- or DHA-induced apoptosis in breast cancer (MDA-MB-231 and MCF-7) cells, associated to a reduction of Bcl2 and caspase-8 expression." (PMID 28869531, 2017). "In other words, miR-34a may participate in the regulation of multidrug resistance in breast cancer by down-regulating the expression of BCL-2, CCND1 and NOTCH1." (PMID 29290947, 2017). "Altogether, our findings suggest that miR-34a is an MDR and prognosis indicator of breast cancer, which may participate in the regulation of drug-resistant breast cancer by targeting BCL-2, CCND1, and NOTCH1." (PMID 29290947, 2017). "MiR-195 overexpressing enhanced the radiosensitivity of breast cancer by targeting BCL-2." (PMID 28740507, 2017). "Nicotine increases Bcl-2 expression in breast cancer cell line MCF-7 cells." (PMID 29088845, 2017). "This indicated that miR-34a is involved in the regulation of drug-resistant breast cancer and may target BCL-2, CCND1, and NOTCH1." (PMID 29290947, 2017). "In addition, E2-dependent up-regulation of NGB results pivotal in the hormone induced overexpression of Bcl-2 protein in breast cancer cell line." (PMID 29216269, 2017). "Moreover, it has been reported that OPN activates JAK2/STAT3 signaling and upregulates Bcl-2 and cyclinD1 in human breast cancer cells." (PMID 28505114, 2017). "In fact, our and others published work indicate that miR-204 may play a role in determining chemoresistance, at least partially through the modulation of the anti-apoptotic BCL2 protein, in gastric and breast cancer cells." (PMID 28199974, 2017). "The significant increase in Bax/Bcl-2 ratio detected in treated cells with respect to untreated cells could have an important impact in the regulation of cell fate by interfering with breast cancer cell survival." (PMID 28349991, 2017).
breast carcinoma (continued). "In addition, lemon citrus extract induced apoptosis in MCF-7 breast cancer cells via upregulating the expression of bax and caspase-3 genes, and downregulating the expression of bcl-2 gene." (PMID 28698459, 2017). "In addition to activating the RAS/MAPK pathway, GH can increase the homeo-box A1-dependent expression of BCL-2 as reported in human mammary carcinoma cells." (PMID 28067847, 2017). "Previously, we found that miR-34a could inhibit the proliferation and migration of breast cancer by targeting B-cell lymphoma 2 (Bcl-2), silent information regulator 1 (SIRT1), E2F transcription factor 3 (E2F3) and CD44." (PMID 29037220, 2017). "Catechins such as catechin, GC, and catechin gallate (CG) induced breast cancer cell apoptosis by suppressing the expression of anti-apoptotic factors such as B cell lymphoma 2 (Bcl-2), Bcl-xL, and survivin, accompanied by the inhibition of NFκB, JAK/STAT, and PI3K pathways." (PMID 27483305, 2016). "Strikingly, expression of BCL2 is seen in ~80% of breast cancer patients." (PMID 27746811, 2016). "Higher concentrations of yeast derivatives for example, may induce cell apoptosis via altering intracellular calcium levels and the ratio of Bax and bcl-2 genes, as was demonstrated in human breast cancer cells exposed to heat-killed S. cerevisiae." (PMID 26932223, 2016). "However the levels of Bcl2 rapidly declined and remained lower in AA when compared to CA breast cancer cells treated with cycloheximide." (PMID 27473585, 2016). "We retain that the impaired autophagy could facilitate the irreversible growth arrest of breast cancer cells, induced by Bcl-2 via p27." (PMID 27462784, 2016). "Several years ago, we had reported the results of study that Bcl-2 may be a potent prognostic factor in patients with luminal subtype of breast cancer." (PMID 27619909, 2016). "To explain this paradoxical result, we considered the meaning of bcl-2 expression in breast cancer." (PMID 28105053, 2016). "Nevertheless, in vitro experiments with BCL2 overexpression or silencing in breast cancer cells confirm its pro-survival effects accounting for current pre-clinical and clinical trials involving BCL2 silencing for breast cancer treatment." (PMID 27746811, 2016). "Moreover, Bcl-2 overexpression in glioma, neuroblastoma, melanoma, breast cancer, lung cancer, and vascular smooth muscle cells increases the expression and activity of MMP-2, MMP-9, and uPA." (PMID 26621844, 2016). "In addition, the protein expression of anti-apoptotic genes, such as XIAP, survivin, Bcl-xL and Bcl-2, was inhibited by thymoquinone in breast cancer cells and breast tumor xenograft." (PMID 27529277, 2016). "Similarly, the increment of these four tested transcripts was also observed in breast cancer cells overexpressing bcl-2, even if at different extent." (PMID 26866271, 2016). "Our results indicated that CUR and BBR treatment alone slightly increased the protein levels of p-JNK and Beclin1 and decreased p-Bcl-2 levels in the two breast cancer cell lines, while co-treatment of these two compounds remarkably enhanced the regulatory effects on these proteins." (PMID 27263652, 2016). "Interestingly, addition of the caspase inhibitor markedly suppressed the levels of Bax and cleaved caspase-3 expressions and increased the levels of total PARP, total caspase-3 and Bcl-2 expressions in the two breast cancer cell lines." (PMID 27263652, 2016). "They concluded that measuring bcl-2 expression in tumor biopsies was an independent predictor of breast cancer outcomes and could be useful as a prognostic adjunct to NPI, particularly in the first 5 years after diagnosis." (PMID 27501955, 2016).
breast carcinoma (continued). "In order to identify whether or which Bcl-2 family members are involved in COX-2+ TAMs-induced breast cancer cell survival, the common anti-apoptotic proteins (Bcl-2 and Bcl-xl) and pro-apoptotic proteins (Bax, Bad and Bid) were detected by Western blot." (PMID 26359357, 2015). "TAMs induced Bcl-2 and decreased Bax expression in breast cancer cells." (PMID 26359357, 2015). "Recent experiments tested the hypothesis that the inhibition of the IGF1R/Akt/Bcl-2/Bax pathways is responsible for the apoptotic effects of genistein in MCF-7 breast cancer cells." (PMID 26694341, 2015). "In addition, hTERT was also observed to be involved in apoptosis by interfering bcl2 expression and function in breast cancer cells, which suggests broad interplay between bcl2 and hTERT in regulating cancer cell survival." (PMID 26472030, 2015). "The balance between pro- and anti-apoptotic members of the Bcl-2 family controls mitochondrial membrane integrity and overexpression of the anti-apoptotic Bcl-2/Bcl-xL proteins correlates with chemoresistance in human leukemia, breast cancer and chondrosarcoma." (PMID 29061939, 2015). "This evidence warrants a clinical study of Bcl-2-targeted therapy in breast cancer." (PMID 26472348, 2015). "Thus, it will be interesting to investigate the function of Bcl-2 induced EMT in the stemness of human breast cancer stem-like cells." (PMID 26091803, 2015). "Furthermore, metastatic human breast cancer cell lines with high Bcl-2 levels were less sensitive to taxanes and Adriamycin." (PMID 25784482, 2015). "ER induces transcription of Bcl-2 in breast cancer cells upon estrogen stimulation." (PMID 25848915, 2015). "In breast cancer, however, Bcl-2 expression has been reported to be a favorable prognostic factor." (PMID 26472348, 2015). "However, EVO initiated atypical apoptosis in fibroblasts and breast cancer cells by inducing cell cycle arrest at the G0/G1 phase with reduced amounts of Bcl-2, cyclin D1, and CDK." (PMID 26207989, 2015). "Many studies have examined the clinical importance of Bcl-2 expression in breast cancer." (PMID 26472348, 2015). "MCL1 is also genetically amplified in 9% of luminal B breast cancers and 54% of TNBCs after treatment with neoadjuvant chemotherapies, suggesting that Mcl-1 may represent a more desirable target over Bcl-2/Bcl-xL in some breast cancers." (PMID 25784482, 2015). "Bcl-2 expression was immunohistochemically evaluated and compared with other clinicopathological factors, including clinical outcome, in 1081 breast cancer cases with long follow-up, separately analyzing 634 cases without any adjuvant therapy and 447 cases with tamoxifen monotherapy." (PMID 26472348, 2015). "The interaction between hyaluronan and CD44 activates the stem cell marker Nanog, Stat-3-mediated MDR1 gene expression, and ankyrin-regulated multidrug efflux in breast and ovarian tumor cells, and it can also lead to Bcl-2 expression and chemoresistance in breast cancer cells." (PMID 25605243, 2015). "In our opinion the presence of Bcl-2 indicates a more aggressive course of breast cancer." (PMID 26112049, 2015). "We constructed a large systematic study to determine whether Bcl-2 has an independent role in breast cancer." (PMID 26472348, 2015). "Thus, it is possible that the decreased CA1 expression in the cultured breast cancer cells suppressed the anti-apoptotic role of BCL2, resulting in increased levels of apoptosis in the treated cells." (PMID 26459317, 2015). "Taken together, these studies suggest that anti-apoptotic Bcl-2 proteins may cooperate with pro-proliferative signals to support breast cancer initiation and progression." (PMID 25784482, 2015). "Recently, it has been reported that silibinin induced the LC3-II expression which closely correlate with the number of autophagosomes, as well as Atg12-Atg5 formation were increased, elevated expression of Beclin1 which was accompanied by a decreased level of Bcl-2 in MCF7 breast cancer cells." (PMID 26311737, 2015).
breast carcinoma (continued). "Interestingly, we found that ATA triggered ER and oxidative stresses, induced loss of MMP, and altered protein expression of Bcl-2, Bcl-xL, and Bax in HER2-positive breast cancer cells." (PMID 26068969, 2015). "Bcl-2 is also a critical biomarker for female breast cancer in predicting patient survival." (PMID 23755153, 2014). "BCL2 signaling is critically important to the maintenance of the antiestrogen resistance phenotype in ER + breast cancer cells, highlighting a possible pro-tumorigenic role of parkin in breast cancer." (PMID 25699171, 2014). "Lapatinib has been shown to inhibit the HER2 downstream signaling pathways RAF/MEK/ERK (ERK cascade) and PI3K/AKT/mTOR and lead to up-regulations of BIM (BCL-2–interacting mediator of cell death) and BID (BCL-2 antagonist of cell death) in HER2-overexpressed breast cancer cells." (PMID 24947902, 2014). "Celecoxib induces apoptosis in breast cancer cells by differential regulation of Bcl-2 and Bax." (PMID 24923427, 2014). "We believe that this subtype represents de-differentiated luminal breast cancers, since BCL2 expression had been preserved in most cases, an anti-apoptotic protein frequently expressed in luminal A and luminal B breast cancer but generally not in HER2 positive or TNBC tumors." (PMID 25296970, 2014). "There are a few reports, in which prognostic potential of BCL-2 expression was investigated in the breast cancer patient groups consisting of subgroups of women treated with ATC in adjuvant setting, although in all these studies, expect one not analysed separately." (PMID 25005788, 2014). "In addition, our results demonstrated that anti-miR-21 inhibitor not only downregulates Bcl-2/IAP expression but also increases chemosensitivity in HA-treated breast cancer cells." (PMID 24606718, 2014). "Additionally in breast cancer cells estradiol was shown to stimulate, while progesterone inhibited Bcl-2 protein expression." (PMID 23755153, 2014). "The ratios of the apoptosis regulating proteins Bcl-2 to Bax and Bcl-XL to Bax were higher in breast cancer cells overexpressing PTHrP but not in NLS-mutated PTHrP overexpressing cells." (PMID 23822995, 2013). "We hypothesize that NLK might be involved in the degradation of c-Myb and that its target genes c-myc and bcl-2 might be potential prognostic factors for breast carcinoma." (PMID 23935942, 2013). "Interestingly, we observed a significant increase in the antiapoptotic transcript BCL-2 in MCF-7 breast cancer cells with reduced Par-4 expression, corroborating the literature regarding the inverse correlation between Par-4 and BCL-2 expression." (PMID 23760770, 2013). "Bcl2 is well known as an anti-apoptotic oncogene in lymphoma, however the paradoxical function of the tumor suppressor gene has been reported in many solid tumors, including breast cancer." (PMID 23573235, 2013). "We demonstrated that that when breast cancer cells had been treated with different doses of embelin for 48 h, Bax and Bcl-2 migrated, the mitochondrial membrane potential increase expression of Bax, while Bcl-2 expression decreased and cytochrome C was released." (PMID 23425971, 2013). "Moreover, BCL2 and E-cadherin were evaluated in primary invasive breast cancers and in synchronous lobular carcinomas in situ (LCIS)." (PMID 24023670, 2013). "The biological mechanisms of Bcl2 as a prognostic factor for breast cancer remain largely unclear." (PMID 23573235, 2013). "Bcl-2 is over expressed in a high percentage of human breast cancer cells." (PMID 24494074, 2013). "In addition, Bcl-2 overexpression increased the metastatic potential in human breast cancer cell lines." (PMID 24098503, 2013). "Altogether, our results strongly argue for the use of the γ-secretase inhibitors in breast cancer therapy, especially in combination with Bcl-2/Bcl-xL inhibition, which may help to reduce the dose of GSI used." (PMID 22703841, 2012). "Breast cancer cells often express high levels of Bcl-2, Bcl-xL, and/or Mcl-1." (PMID 22703841, 2012).
breast carcinoma (continued). "Furthermore, the expression of bcl-2, a marker of good prognosis in breast cancer, was higher and HER2/neu expression was lower in screen-detected cancers than in symptomatic cancers (OR = 1.77, CI = 1.01-3.23 and OR = 0.64, CI = 0.40-0.98, respectively)." (PMID 23244222, 2012). "Considering that the PI3K subunit p85, NF-kB and Bcl2 are inhibited by plumbagin in human breast cancer cells, this result suggests that its3 is a new molecular target of plumbagin and possibly contributes to the cytotoxic activity of this agent in human cancers." (PMID 23028742, 2012). "Thus, our results highlight the clinical relevance of targeting γ-secretase and downstream Notch signaling in breast cancer, especially in combination with the Bcl-2/Bcl-xL inhibitor ABT-737." (PMID 22703841, 2012). "A multivariate analysis incorporating five published studies from 11,212 breast cancer cases strongly supported the independent prognostic significance of BCL2 positivity with improved survival (Hazard Ratio (HR) 0.76, 95% Confidence Interval (CI) 0.54-0.74), p <0.001)." (PMID 23961365, 2012). "The association between gemcitabine resistance and Bcl-2 expression was further examined in 3 breast cancer cell lines and 3 gastric cancer cell Consistently, MCF-7 breast cancer cell line and YCC16 gastric cancer cell line that had high Bcl-2 expression were resistant to gemcitabine." (PMID 23226540, 2012). "Ki67 and Bcl-2 have been reported to correlate with the malignancy of breast cancer." (PMID 23342282, 2012). "Interestingly, this observation is supported by a recent report that shows that the co-silencing of Bcl-2, Bcl-xL, and Mcl-1 in breast cancer cell lines potently reduced mammosphere formation." (PMID 22703841, 2012). "Several studies indicate that ER may be implicated in breast cancer cell survival via cross-talk with the PI3K/Akt pathway, or by regulating the activity of NF-κB, Bcl-2, or IAP family members." (PMID 22776333, 2012). "In addition, expression of BCL2 has been proven to be an independent indicator of favourable prognosis for all types of early-stage breast cancer." (PMID 23961365, 2012). "In the present study, we aimed to determine if ABT-737, a BH3-only mimic, could reverse the acquired radioresistance of the breast cancer cell line MDA-MB-231R by targeting Bcl-2 and Bcl-xL." (PMID 23259599, 2012). "miR-21 can also inhibit apoptosis in breast cancer cells by regulating Bcl2 expression." (PMID 22363450, 2012). "Therefore, we determined the correlation between ERE transcriptional activity and mRNA expression levels of Ki67 and Bcl-2 in Luminal A breast cancer samples." (PMID 23342282, 2012). "Previously, bcl-2 was found to be reduced in breast cancer cell lines when treated with bDLE." (PMID 22044844, 2011). "Different Bcl-2 protein levels in breast cancer cell lines were determined using western blot." (PMID 21457555, 2011). "The different results in CLL and breast cancer may be determined by the balance between the dual function of Bcl-2 protein." (PMID 21457555, 2011). "Moreover, antiestrogen resistant breast cancer cells MCF7/LCC9 have greater BCL2 protein expression compared to antiestrogen sensitive breast cancer cells (MCF7/LCC1)." (PMID 22295238, 2011). "To determine whether MYB acts directly on the BCL2 gene in breast cancer cells, we performed ChIP assays using MCF-7 cells." (PMID 20659323, 2010).